TNF (tumor necrosis factor)
Diseases named in the same sentence as TNF in open-access papers (continued):
Sharing a sentence is not in itself a finding about the gene and the disease.
schizophrenia (continued). "Only one previous study reported a significant positive correlation between levels of TNF-α and IL-1β in schizophrenia patients." (PMID 29867314, 2018). "How the interaction between TNF-α and IL-1β is participated in the pathogenesis of schizophrenia warrants the further investigation." (PMID 29867314, 2018). "Increased levels of nterleukin (IL) 1-β, IL-2, IL-6, IL-8, IL-12, transforming growth factor-beta (TGF-β), and tumor necrosis factor-alpha (TNF-α) were detected in patients with schizophrenia than in controls." (PMID 30245643, 2018). "For reason of the disease state, illness duration, medication, the timing of the assays and so on, the reports on levels of TNF-α and IL-1β in schizophrenia have been inconsistent." (PMID 29867314, 2018). "The underlying mechanisms for the decreased TNF-α and IL-1β levels in FEDN patients with schizophrenia should be further investigated." (PMID 29867314, 2018). "al reported that schizophrenia patients had significantly overexpressed TNF-α and IL-1β in blood mononuclear cells." (PMID 29867314, 2018). "In the case of TLR4 stimulation, there were significantly weaker IL-1β, IL-6, and TNF-α responses in schizophrenia relative to the control subjects (p < 0.01), whereas IL-10 production was intact (p > 0.5)." (PMID 28646138, 2017). "We found an overall decrease in the anti-inflammatory IL-2 mRNA (p = 0.006) and an increase in three serum cytokines, IL-6 (p = 0.010), IL-8 (p = 0.024) and TNFα (p < 0.001) in people with schizophrenia compared to healthy controls." (PMID 28923068, 2017). "This shows TNFα was increased in both the elevated and low cytokine subgroups of people with schizophrenia in serum." (PMID 28923068, 2017). "For IL-1β, IL-6 and TNF-α, we observed a significantly higher response in schizophrenia patients than in control subjects (p < 0.05)." (PMID 28646138, 2017). "For example, there are studies reporting elevated levels of TNF-α and IL-8 in perinatal period of adult patients with schizophrenia." (PMID 28358316, 2017). "Nonetheless, inflammatory processes appear to play a key role in schizophrenia, and CRP has been widely regarded as a state marker in schizophrenia alongside other cytokines like tumor necrosis factor-alpha." (PMID 29404313, 2017). "In our analysis of protein levels of cytokines, we found significant increases in serum protein levels for the cytokines IL-6, IL-8 and TNFα in the whole group of people with schizophrenia compared to the whole group of healthy controls." (PMID 28923068, 2017). "We have also shown higher levels of three pro-inflammatory cytokines IL-6, IL-8 and TNF-α in the serum of people with schizophrenia, indicating a role of moderate chronic inflammation in schizophrenia." (PMID 28923068, 2017). "Both protein and mRNA levels of IL-1β, TNF-α, and microglial markers were significantly increased in postmortem schizophrenia brains in relation to the brains of comparison subjects." (PMID 28396623, 2017). "Altered expression of another schizophrenia-related gene, TNF, was borderline significant on the PCR arrays, with a p-value = 0.013100." (PMID 29302405, 2017). "The higher levels of IL-6 and TNF-α (7.98±.67 and 40.76±6.98 pg/ml) were recorded in the newly diagnosed schizophrenia patients." (PMID 28083028, 2016). "A meta-analysis of cytokine changes in the peripheral blood has identified IL-2, IFN-gamma, TNF-alpha and soluble IL-2 receptor as trait markers of schizophrenia because their levels were elevated during acute exacerbations and reduced in remission." (PMID 25563714, 2015). "A meta-analysis of cytokine changes in the peripheral blood has identified IL-12, IFN-gamma, TNF-alpha, and soluble IL-2 receptor (sIL-2R) as trait markers of schizophrenia because their levels were elevated during acute exacerbations and remission." (PMID 25563714, 2015).
schizophrenia (continued). "Increased serum levels of tumor necrosis factor (TNF)-α at birth have also been found in mothers whose child subsequently developed schizophrenia or other psychotic disorders." (PMID 24146637, 2013). "Cytokine alterations in schizophrenia have been comprehensively investigated in adult schizophrenic patients, with IL-1, 2, 6, 8, 10, and 12 all been observed to increase in schizophrenia, along with TNFα, TGF-β 1, and IFNγ." (PMID 23805069, 2013). "Offspring of poly I:C treated dams also displayed increased levels of plasma TNF-α at PND 55 mirroring alterations in cytokines levels reported in people with schizophrenia." (PMID 23738203, 2012). "Viral recognition by microglial Toll-like receptors (TLR2, TLR3, TLR9) triggers robust neuroinflammatory responses characterised by elevated key pro-inflammatory mediators such as IL-6, TNF-α, and IL-1β, patterns consistently observed in patients with schizophrenia." (PMID 40806558, 2025). "Second, differences in methods of measuring TNF-α, recruiting patients at different stages or with different types of schizophrenia, and using different antipsychotic medications may also affect study results." (PMID 40791199, 2025). "Stimulation of whole blood cells from SZ patients with selective TLR agonists results in enhanced release of pro-inflammatory cytokines (including IL-1β, IL-6, IL-8, and TNF-α), further supporting the role of TLRs in regulating neuroinflammation in schizophrenia." (PMID 41346597, 2025). "Furthermore, the resulting pro-inflammatory cytokine discharge, including interleukin-1β (IL-1β), IL-6, and TNF-α, and the disruption of the blood–brain barrier can collectively lead to the neurodevelopmental abnormalities characteristic of schizophrenia." (PMID 40806558, 2025). "Similar to IL-6, TNF-α is associated with more severe negative symptoms in schizophrenia and other psychotic disorders." (PMID 39858450, 2025). "Moreover, the exacerbation of schizophrenia symptoms is associated with raised concentrations of IFN-γ, TNF-α, IL-12, and sIL2R." (PMID 40364201, 2025). "Also, another meta-analysis with a large scale of 59 studies found first-episode patients (FEP) with schizophrenia have higher levels of IL-6 and TNF-α than the general population." (PMID 38352871, 2024). "Together with a significant reduction in pro-inflammatory factor TNF-α after 10 sessions of ECT suggests that ECT may work in part by reducing inflammation in the treatment of schizophrenia." (PMID 38233774, 2024). "Notably, TNF-α has been identified as prognostic indicators for the emergence of MetS in patients with schizophrenia during antipsychotic treatment." (PMID 38627438, 2024). "In schizophrenia, the transmembrane TNFα is considered a novel target for schizophrenia, and its receptor TNFR2 may be an important factor that mediates immune signaling." (PMID 38592583, 2024). "Corroboratively, overexpression of this and other proinflammatory cytokines including IL-6 and tumor necrosis factor (TNF) in isolated CD14+ (classical) monocytes from schizophrenia patients was also found by earlier studies, showing particularly evident in patients with active psychosis." (PMID 38532012, 2024). "In the context of schizophrenia, researchers have found evidence of cytokines such as C-reactive protein (CRP), IL-1β, IL-6, IL-12, interferon-γ, and tumor necrosis factor α (TNF-α) being associated with endophenotypes and varying disease status of schizophrenia." (PMID 38445386, 2024). "In schizophrenia, meta-analyses have supported the hypothesis of a decrease in Th1 immunity (IL-1 and TNF-α) in first-episode drug-naïve persons." (PMID 37510730, 2023). "PUFAs reduce neuroinflammation and, in patients with schizophrenia, result in a reduction in proinflammatory cytokines, such as IL-6 and TNF-α; a reduction in CRP; and an increase in BDNF, which, due to its neurotrophic action, has positive effects on cognition function." (PMID 37371435, 2023).
schizophrenia (continued). "However, they did discover a significant association between the combination of the BDNF gene (rs6265 AA/AG) and the TNF-α gene (rs1799964 CC/CT) and the development of schizophrenia." (PMID 37763162, 2023). "Furthermore, there was a positive correlation between serum TNF-α levels and cognitive function in schizophrenia patients." (PMID 37189796, 2023). "While genes such as TCF7L2, TNF, APOE and BDNF-related genes can heighten T2DM and schizophrenia risk, other genes may have opposing impacts and lead to inconsistent and biased LDSR findings." (PMID 37477360, 2023). "The level of TNF-α in patients with a chronic course has also been increased, which might be a hint for TNF-α ability related to schizophrenia’s course." (PMID 37644489, 2023). "Indeed, increased IL-6, TNF-α, and other pro-inflammatory cytokines have been consistently implicated in psychiatric disorders, specifically, ASD, schizophrenia, and bipolar disorders." (PMID 37355708, 2023). "Schizophrenia studies have found higher IL-6 levels in the CSF than in the blood and lower IL-1β CSF levels compared to those in the blood, as well as lower levels of IL-1β, IL-6, and TNF-α and higher IL-8 levels in the CSF than in the blood of MDD subjects." (PMID 37510730, 2023). "Thus, the revealed complex of immunological indicators (IL-8, CIC, IL-4, IFN-γ, TNF-α, cortisol) is significant for diagnosing schizophrenia." (PMID 39944368, 2023). "APZ offers anti-inflammatory benefits, both alone and when used in combination with other antipsychotic medications, leading to a reduction in various inflammatory parameters, including vulnerable inflammatory cytokines like TNF-α and interleukins (ILs), in individuals with schizophrenia." (PMID 38256307, 2023). "Moreover, increased neurotoxicity caused by increased levels of toxic cytokines (e.g., IL-1β, IL-6, IL-8, TNF-α, and IFN-γ) and chemokines (e.g., CCL11, CCL2, CXCL8, and CXCL10) is significantly associated with the G-CoDe and the schizophrenia phenome." (PMID 36256663, 2022). "The mechanisms by which clozapine causes inflammation are not fully understood; nevertheless, it has been reported that pro-inflammatory cytokines, such as interleukin-6 (IL-6) and tumor necrosis factor-α (TNF-α), are elevated in patients with schizophrenia treated with clozapine." (PMID 36271340, 2022). "TNF-α produced by microglia appears to act in cognitive dysfunction in patients with schizophrenia." (PMID 35887634, 2022). "Tumor necrosis factor α (TNF-α) is an important pro-inflammatory factor that may play an important role in the pathogenesis of schizophrenia by stimulating nerve regeneration and maintaining an inflammatory state." (PMID 36246695, 2022). "HPA-axis dysregulation associated with hypercortisolemia has been reported in psychotic patients and might be elicited by pro-inflammatory cytokines such as IL-1, IL-6, and TNF-α in schizophrenia." (PMID 35963926, 2022). "TNF-α levels have been found to be increased in schizophrenia patients." (PMID 35844244, 2022). "CCL2, coming from either myeloid cells or astrocytes, can influence the differentiation of tissue macrophages and promotes the production of proinflammatory cytokines including IL-6, IL-1β, and TNF-α which are all elevated in the brains of people with high inflammation schizophrenia." (PMID 35844224, 2022). "Therefore, it is likely that elevated FcGR3A contributes to the pattern of increased levels of IL-1β, IL-6, and TNFα in the midbrain which can be used to define the high-inflammation biotype of schizophrenia." (PMID 35841099, 2022). "Blood biochemical markers GPX1, MDA1, CAT1, and TNF-α may play an important role in the pathogenesis of schizophrenia combined with TD patients, and they may be useful in the diagnosis of schizophrenia with tardive dyskinesia." (PMID 35299866, 2022).
schizophrenia (continued). "Our finding of increased TNFR2 mRNA in the blood of patients therefore suggests that TNF signaling in people with schizophrenia is slanted toward pro-survival immune cell activation that may promote immune cell survival and/or sustain inflammation." (PMID 35027554, 2022). "Furthermore, increased levels of IL-1β, IL-6, IL-17, IL-21, IL-22, IL-23, and tumor necrosis factor (TNF)-α were all found to be inversely related to HR-QoL in these schizophrenia patients." (PMID 36011997, 2022). "Furthermore, there is no significant increase in IL-1β levels in chronic patients, and there are diminished IL-1β and TNF-α levels in first-episode schizophrenia with a disease duration of less than 2 years." (PMID 36556337, 2022). "In conclusion, TNF-α could influence the Kyn pathway in chronic hospitalized patients with schizophrenia." (PMID 34393855, 2021). "Such an IL-8 increase may be related to the activation of monocytes and macrophages, as IL-1 and TNF-α released from these cells have been shown to be elevated in schizophrenia." (PMID 33746786, 2021). "Certain authors report an increase in serum TNFα among patients with schizophrenia." (PMID 38601098, 2021). "Amounting evidence has revealed the activated TNF pathway in schizophrenia." (PMID 34526062, 2021). "Beyond IL-6, TNF-α is associated with schizophrenia-negative outcome, and thus can be considered a novel drug target for schizophrenia therapy." (PMID 33746786, 2021). "Such elevated levels of IL-8, IL-6, and TNF-α imply that schizophrenia might represent an autoimmune neuropsychiatric spectrum disorder that may emerge during an autoimmune CNS disease." (PMID 33746786, 2021). "Likewise, IL-12, IL-6, TNF and IFNγ peripherical levels are enhanced in patients with schizophrenia, and IL-6 and IL-10 levels elevated in children with ADHD." (PMID 34610039, 2021). "One meta-analysis showed that acutely relapsed patients with schizophrenia have increased levels of peripheral interleukins (IL) including IL-6, IL-8, tumor necrosis factor alpha (TNF-α), interferon gamma (IFN-γ) but reduced levels of IL-10 when compared with healthy controls." (PMID 33667853, 2021). "Interestingly, in a study of post-mortem brain samples in individuals with Schizophrenia and bipolar disorder, the levels of TNF-α were negatively correlated with those of Adam17, suggesting anti-inflammatory properties for this gene." (PMID 34573170, 2021). "Our study found that the TNF-α levels in FEDN patients with schizophrenia before treatment were significantly higher than those in healthy controls and chronic patients and that the TNF-α levels before treatment were significantly positively related to changes in PANSS negative symptoms." (PMID 34763685, 2021). "This is in line with our finding that TNF predicted slower performance in patients with schizophrenia on both the TMT and SC tasks, which comprise two out of the three processing speed items from the MCCB, as well as our psychomotor component derived from the PCA." (PMID 32238816, 2020). "In addition, after 6 weeks of treatment with four different atypical antipsychotics (risperidone, amisulpride, olanzapine, and aripiprazole), patients with schizophrenia exhibited a significant reduction of plasma IL-6 and TNF- α." (PMID 32061259, 2020). "Hence, IDO is upregulated by cytokines such as IFN-γ and TNF-α, and in schizophrenia, increased TNF-α has been observed." (PMID 32226399, 2020). "IL-6 and TNF-α levels are elevated in schizophrenia and animal models." (PMID 32296347, 2020). "Long-term treatment of olanzapine caused metabolic symptoms, including IR, by markedly elevating the plasma levels of pro-inflammatory cytokines, including IL-1ß, IL-6, IL-8 and TNFα; these findings are consistent with observations from schizophrenia patients chronically treated with olanzapine." (PMID 30733507, 2019).
schizophrenia (continued). "Patients with first episode of schizophrenia as well as its relapse were reported to have increased serum level of IL-6, tumor necrosis factor α, IL-1β, and interferon-γ and decreased serum concentration of anti-inflammatory interleukin-10 (IL-10) (Müller 2018)." (PMID 30178287, 2019). "Both TNF-α and IL-1β were among the mostly reported cytokines in schizophrenia." (PMID 29867314, 2018). "Thirdly, we did not collect some important clinical information, such as smoking, BMI and other data, which may affect the TNF-α and IL-1β levels in schizophrenia patients." (PMID 29867314, 2018). "On the other hand, it has been suggested that an increased level in plasma of pro-inflammatory cytokines such as IL-8 (interleukin-8) and tumor necrosis factor-α (TNF-α) during pregnancy could be related to offspring schizophrenia in adulthood." (PMID 30483218, 2018). "In fact, patients with post-traumatic stress disorder, typically caused only due to intense psychological stress, also exhibited an elevation in peripheral TNF-α levels, which were reproducibly reported in other psychiatric diseases as well, including schizophrenia." (PMID 29593588, 2018). "A significantly elevated level of TNF-α in the plasma of schizophrenia patients was found." (PMID 30254506, 2018). "Few studies has explored the interaction between TNF-α and IL-1β in patients with schizophrenia." (PMID 29867314, 2018). "It has been observed in preclinical studies that maternal immune activation in rodents induces inflammatory cytokines (IL-1β, IL-6, TNF) and reduces anti-inflammatory cytokines (IL-10) in both the maternal fluids and in the fetal brain, inducing schizophrenia-like behaviors in the offspring." (PMID 28620379, 2017). "TNFα has recently been reported to also be upregulated in the plasma of people with schizophrenia." (PMID 28923068, 2017). "An elevated level of TNF-α has been found in patients with schizophrenia." (PMID 29317797, 2017). "Additionally, a missense mutation in NRG1 has been reported to increase activation of proinflammatory cytokines such as interleukin 6 (IL-6), tumor necrosis factor α (TNF-α), and interleukin 8 (IL-8) in patients with schizophrenia." (PMID 27725886, 2016). "They established that pro-inflammatory cytokine levels are constantly augmented in patients with schizophrenia and stated that pro-inflammatory cytokines like IL-6, IL-12, TNF-α, IL-1β, and IFN-γ are elevated in the blood and CSF in initial-onset and acute-relapse patients with schizophrenia." (PMID 27047333, 2016). "Pro-inflammatory changes include elevated serum measures of pro-inflammatory cytokines [interleukin (IL)-1β, IL-6, IL-8, TNF-α] and other pro-inflammatory factors [prostaglandin E2 (PGE2), CRP] and elevated monocyte counts and activated immune cells have been associated with schizophrenia." (PMID 24550848, 2014). "Additionally, injection of IL-6, but not the other MIA-induced cytokines IL-1α, tumor necrosis factor α (TNFα), or interferon γ (IFNγ), during pregnancy was enough to cause PPI deficits, a hallmark of schizophrenia, in offspring." (PMID 25691854, 2014). "Moreover, maternal levels of TNF-α were significantly elevated among individuals with schizophrenia, with evidence of increasing odds of psychosis in relation to higher cytokine levels." (PMID 23805069, 2013). "Moreover, interactions between inflammatory cytokines such as tumor necrosis factor-α (TNF-α) and MDA are risk factors in first episode drug-naïve schizophrenia, suggesting that inflammatory factors and OS and their interactions are involved in the pathogenesis of schizophrenia." (PMID 38172869, 2024). "First, the study was based on a cross-sectional design and could not investigate the direct causality between TNF-α and the development of agitation in patients with schizophrenia." (PMID 38956509, 2024). "Additionally, the TNF-α and TNF-α-related signaling pathways may be crucial in the pathophysiology of schizophrenia." (PMID 37189796, 2023).